HLA-G (major histocompatibility complex, class I, G)
Diseases named in the same sentence as HLA-G in open-access papers (continued):
Sharing a sentence is not in itself a finding about the gene and the disease.
tumor (continued). "JNJ-78306358 is another drug that redirects T-cells through CD3 to target and kill tumor cells expressing human leukocyte antigen-G (HLA-G)." (PMID 41211166, 2025). "Given its tumor-specific expression and immune inhibitory function and its anti-tumor efficacy further solidified by pre-clinical HLA-G-targeted in vitro and in vivo studies, HLA-G is expected to act as a promising immune checkpoint." (PMID 41181133, 2025). "Tumor cells upregulate inhibitory ligands such as HLA-E, HLA-G, and PD-L1, which interact with NKG2A, KIRs, and PD-1, leading to profound suppression of NK cells cytotoxicity." (PMID 41562080, 2025). "HLA-G+, PD-1+, and PD-L1+ EVs contribute to immune dysfunction in MM and represent promising targets to restore anti-tumor immunity." (PMID 40948764, 2025). "This early finding framed HLA-G as a tolerogenic molecule, but subsequent studies revealed that its influence extends far beyond reproduction, encompassing tumor biology, transplantation, infection, and autoimmunity." (PMID 41445738, 2025). "•Tumor-derived molecules such as PD-L1, PD-L2, and HLA-G suppress immune cell activity, facilitating immune evasion and tumor proliferation." (PMID 40242222, 2025). "Among patients with benign lesions, previous neoplasm was related to higher LEVs-HLA-G+ count (p=0.001) and int-HLA-G levels (p=0.03)." (PMID 41268555, 2025). "The tolerogenic HLA-G molecule mediates tumor immune evasion by binding to inhibitory receptors on the surface of immune effector cells." (PMID 40584831, 2025). "Their interactions with different immune molecules, including PD-L1, PD-L2, HLA-G, and tumor-infiltrating cells, such as T-cells, facilitate immunological escape in EwS." (PMID 40242222, 2025). "By interacting with KIR receptors on NK cells, HLA-G contributes to the suppression of NK cell activity, allowing tumor cells to escape immune-mediated destruction." (PMID 41234446, 2025). "This concept is supported by the identification of HLA-G+ EVs in various tumor types, where their presence correlates with disease progression." (PMID 40948764, 2025). "Overall, the transfer of immune stimulatory or regulatory molecules—CD80, CD86, OX40L, HLA-G, and PD-L1—via trogocytosis significantly inhibits anti-tumor immunity and contributes to the development of the immune-suppressive tumor microenvironment." (PMID 39741180, 2025). "Those nevi individuals whose experienced an oncologic disease of some type of neoplasm showed considerable increases in LEVs-HLA-G+ (p=0.001) and int-HLA-G (p=0.03)." (PMID 41268555, 2025). "LILRB2 is known to inhibit immune cell activity and modulate the tumor immune microenvironment through its interaction with ligands such as HLA-G, angiopoietin-like protein 2, and semaphorin-4A, thereby promoting tumor cell proliferation and metastasis." (PMID 41383852, 2025). "KIR2DL4 stands out among KIRs for its distinct capacity to interact with HLA-G, a ligand frequently overexpressed on tumor cells as a means of evading immune surveillance." (PMID 40549069, 2025). "Given the central role of IFN-γ in orchestrating anti-tumor responses, this finding underscores the immunosuppressive capacity of HLA-G–expressing EVs." (PMID 40948764, 2025). "HLA-G can drive macrophage polarization towards the M2 phenotype, marked by immunosuppressive functions that inhibit T-cell responses and advance tumor progression by releasing various growth factors." (PMID 40242222, 2025). "HLA-G is involved in tumor evasion by hindering cytolysis, suppressing the stimulation of cytokines, inducing apoptosis of immune cells, and impairing chemotaxis." (PMID 38384647, 2024). "We plan to analyse other HLA-G 3′UTR variants and determine their impact on HLA-G expression in HNSCC patients, as has been shown in other tumor types." (PMID 38391781, 2024).
tumor (continued). "This successfully validates the results of the microarray analysis showing that the neo-expression of HLA-G in RCC7 tumor cells simultaneously modifies genes involved in different biological pathways." (PMID 39358558, 2024). "Before proceeding further with a more thorough analysis of the effect of HLA-G in tumor cells, we performed an expression validation of the transcriptome results by RT-PCR." (PMID 39358558, 2024). "The extensive immunosuppression was orchestrated due to the rapid spread of HLA-G, which was originally restricted in expression, to more kinds of cells and larger areas, enhancing the capacity of the whole tumor to counteract the immune system." (PMID 38310272, 2024). "Concurrently, elevated levels of HLA-G and an increase in regulatory T cells (Tregs) further impede the activation of tumor-specific T cells." (PMID 38427643, 2024). "To study potential gene modification triggered by the neo-expression of HLA-G in tumor cells, we compared gene expression profiles of RCC7 cells expressing or not HLA-G." (PMID 39358558, 2024). "Based on internal immunohistochemistry (IHC) data, RCC, OC and CRC emerged as tumor types with the highest prevalence of HLA-G expression." (PMID 39105878, 2024). "At the same time, HLA-G molecules allow tumor cells to elude the killing and dissolving actions of NK cells and cytotoxic T cells, which is a strategy for tumor cells to avoid immune surveillance." (PMID 38577332, 2024). "Analyses of the associations between local HLA-G mRNA expression in tumor urine cells and/or soluble HLA-G serum levels and the selected variables including tumor grade, disease stage, and BMI were performed in BC patients." (PMID 39594832, 2024). "Antibodies, particularly targeting HLA-G1, obstruct the ability of NK cells to eliminate tumor cells, highlighting HLA-G's role in immune evasion." (PMID 38384647, 2024). "Increased mRNA expression of ILT2 and ILT4 in early tumor development should be explained by the heterogeneity in HLA-G expression and the number of immune cells within tumor tissue." (PMID 38391781, 2024). "A positive correlation between HLA-G expression and advanced disease stage, tumor metastasis, poor prognosis, and shorter DFS has been reported in many cancer types." (PMID 39594832, 2024). "JNJ-78306358 is a bispecific antibody that redirects T cells to kill human leukocyte antigen-G (HLA-G)-expressing tumor cells." (PMID 39105878, 2024). "Antibodies against HLA-G molecules present on the exterior of malignant cells, in fusion with other anti-cancer drugs, are essential for anti-tumor activity." (PMID 38384647, 2024). "Inter-patient, inter-tumor and intra-tumor heterogeneity in HLA-G expression, as well as tumor-infiltrating immune cells in various types of malignancies, has been described previously." (PMID 38391781, 2024). "Altogether, the data generated in this study provided a more comprehensive understanding of the complex mechanisms behind the cross-talk between tumor and immune cells and highlighted, for the first time, potential HLA-G partners." (PMID 39358558, 2024). "Remarkably, Nb‐TriTE exhibits the ability to recognize all HLA‐G isoforms and retains the capacity to bind HLA‐G expressed on tumor cells despite interference from soluble HLA‐G isoforms." (PMID 39234811, 2024). "The extremely high reduction in CLU and DSC2 levels found in our microarray study following HLA-G expression is consistent with HLA-G-favoring tumor progression." (PMID 39358558, 2024). "All those markers are expressed in exhausted T cells and are considered to be involved in a defective anti-tumor immune response, thus indicating a potential immunosuppressive infleunce of HLA-G tumor cell expression." (PMID 39469714, 2024). "Ubiquitinated HLA-G complexes have been found in the circulation and unleashed as exosomes, favoring tumor spread." (PMID 38310272, 2024).
tumor (continued). "Specifically, compared with PD‐L1 Nb‐BiTE and HLA‐G Nb‐BiTE, the tumor growth inhibition was superior, and survival was prolonged significantly in mice after treatment with the dual‐targeting Nb‐TriTE in combination with PMBCs." (PMID 39234811, 2024). "Given the caveats of the small sample numbers being assessed, prior treatment history, tumor heterogeneity and the IHC staining platform, the observed prevalence of HLA-G expression broadly agreed with preclinical data." (PMID 39105878, 2024). "We compared the transcriptome of these tumor cells with those in which we induce the expression of HLA-G." (PMID 39358558, 2024). "Recent studies have demonstrated that when HLA-G is highly expressed, tumor cells are more likely to escape from the immune surveillance." (PMID 37981615, 2024). "Interaction between HLA-G on tumor cells and LILRB1-expressing NK cells and CD8+ T cells inhibits cytotoxicity through the ITIM/SHP-2-mediated pathway." (PMID 38785789, 2024). "Taken together, the overall picture emerging from this study is that HLA-G has complex roles in tumor cells than initially anticipated." (PMID 39358558, 2024). "In this study, a nanobody‐based trispecific T cell engager (Nb‐TriTE) is developed, capable of simultaneously binding to T cells, macrophages, and cancer cells while redirecting T cells toward tumor cells expressing PD‐L1‐ and/or HLA‐G." (PMID 39234811, 2024). "Although Nb‐TriTE can bind all HLA‐G isoforms, it had the capacity to recognize membrane‐bound HLA‐G overexpressed on tumor cells even in the presence of interference from soluble HLA‐G isoforms." (PMID 39234811, 2024). "This dynamic can also allow tumor cells to evade immune attack as a greater number of cancer cells express HLA-G in order to protect themselves." (PMID 38954689, 2024). "Potential therapies that reduce the presence of HLA-G in tumors or suppress its transcription prove to enhance the efficacy of NK cells in lysing tumor cells, especially in patients with CLL." (PMID 38384647, 2024). "In vitro studies demonstrated that JNJ-78306358 exhibits peripheral blood mononuclear cell- and T cell- based cytotoxicity against endogenous membrane HLA-G-expressing tumor cell lines with increased potency with increasing HLA-G expression." (PMID 39105878, 2024). "HLA-G expressed by tumor cells can be acquired by immune cells which convert in HLA-G-positive cells reversing their function from effectors to regulatory cells." (PMID 39766165, 2024). "Immune evasion and tumor progression is further facilitated by HLA‐G overexpression in various tumors and its interaction with KIRs on immune cells." (PMID 38882209, 2024). "Human leukocyte antigen‐G (HLA‐G), an ICP as well as a neoexpressed tumor‐associated antigen, is previously demonstrated to be a beneficial target in combination with anti‐PD‐L1." (PMID 39234811, 2024). "Increased expression of HLA-G and its ILTs receptors have been correlated with tumor progression in various cancer types." (PMID 38391781, 2024). "Cai and coworkers had shown that HLA-G expression was found to be associated with the prognosis of HCC, reduced overall survival, and increased tumor recurrence." (PMID 39703498, 2024). "Taken together, these results suggest the successful redirection of T cells to tumor sites by Nb‐TriTE targeting to PD‐L1 and HLA‐G." (PMID 39234811, 2024). "We examined specific genetic variations and measured HLA-G levels in urine and blood samples, also considering factors such as tumor stage, body mass index, and heart rate variability (HRV)." (PMID 39594832, 2024). "To further deepen the understanding of the effect of HLA-G in tumor cells, we carried forward the dissection of the system using inhibitors of specific molecules." (PMID 39358558, 2024).
tumor (continued). "TEVs were originally characterized for their capability to transfer tumor antigens to DCs but are currently regarded as mainly immunosuppressive because of the expression of DC-inhibiting molecules such as PD-L1, HLA-G, PGE2 and others." (PMID 39075551, 2024). "Highly expressed HLA-G and highly inhibited LILRB2 implicated involvement of immune tolerance or anti-tumor immune escape." (PMID 38450191, 2024). "In conclusion, nanobody‐based trispecific T cell engager, Nb‐TriTE, targeting both PD‐L1 and HLA‐G on tumor cells along with CD3ɛ on T cells, offers a promising solution to the shortcomings of monospecific ICP antibodies." (PMID 39234811, 2024). "HLA-G expression has been reported to be modulated by the grading and staging of the tumor, and HLA-G protein levels were significantly higher in patients with advanced stages in comparison to early-stage and normal." (PMID 38310272, 2024). "HLA-G is known to up-regulate PD-1 in tumor infiltrating T lymphocytes, leading to a potential antitumor synergy when combining anti-PD-1/PD-L1 antibodies with HLA-G targeted therapies." (PMID 39766165, 2024). "An analysis of association between HLA-G, ILT2 and ILT4 mRNA expression and the clinical variables age at onset, tumor staging, node involvement, distal metastasis and p16 positivity was performed in HNSCC patients." (PMID 38391781, 2024). "HLA-G directly impaired the cytotoxicity of effector T cells, mitigating the anti-tumor activity of γδΤ cells and facilitating the immune evasion of target cells." (PMID 38310272, 2024). "The HLA-G expression has been frequently detected in bladder cell carcinoma tissues as compared to normal bladder tissues and has correlated with tumor grade." (PMID 39594832, 2024). "It was found that radiotherapy decreased HLA-G expression on tumor cells as well as on tumor-infiltrating mononuclear cells." (PMID 38391781, 2024). "IHC staining results suggest that PD‐L1+ cells and HLA‐G+ cells within tumor burden were significantly reduced after Nb‐TriTE treatment compared with the vehicle group (respectively)." (PMID 39234811, 2024). "Low-dose chemotherapy enhanced the sensitivity of tumor cells to CAR-NK cells by raising HLA-G expression on the surface of tumor cells." (PMID 38310272, 2024). "To this end, we investigate the modifications triggered by the neo-expression of the immune checkpoints HLA-G in ccRCC tumor cells." (PMID 39358558, 2024). "Neoplastic cells express immunoinhibitory molecules (immune checkpoints), such as programmed death ligand-1 (PD-L1), programmed death ligand-2 (PD-L2), and human leukocyte antigen-G (HLA-G) that make them more resistant to attacks by specific tumor T cells." (PMID 38954689, 2024). "The data reveal multifaceted roles of HLA-G in tumor cells which are far beyond the well-known function of HLA-G in the immune anti-tumor response." (PMID 39358558, 2024). "The tumor-specific expression of HLA-G and its biological characteristics, particularly its involvement in tumor immune evasion, render it as an interesting biomarker and a potential therapeutic target for novel immunotherapies." (PMID 39469714, 2024). "This implies that miR-152 can suppress HLA-G, enhancing immune cell-mediated killing of tumor cells and impeding RCC progression." (PMID 39606232, 2024). "By bolstering CLL tumor cells against NK cell-induced killing, HLA-G actively contributes to the immune escape of tumor cells in vivo." (PMID 38384647, 2024). "Given the capacity of all HLA‐G isoforms to regulate the immune system, blocking all HLA‐G isoforms is beneficial for completely disrupting the role of HLA‐G in tumor progression." (PMID 39234811, 2024). "Recent research indicates that tumor cells, cytotrophoblast cells, and mesenchymal stem cells are capable of releasing EVs carrying HLA-G." (PMID 39766165, 2024).
tumor (continued). "Despite the sizable evidence implicating a pronounced overlap in the expression patterns of HLA-G and PD-L1 across different tumors, there is heterogeneity in the areas of expression and levels of expression within the same tumor." (PMID 38310272, 2024). "Inter- and intra-tumoral heterogeneity of HLA-G expression has been observed in several studies of HLA-G at a transcription and protein level, either among patients with different types of neoplasm, or among patients with the same type of solid tumor." (PMID 39766165, 2024). "Subsequently, compared with non-neoplasia nasal epithelial tissues, the expression of HLA-G and NRGN was upregulated in grade I, II, III and IV tissues, while the expression of MAML2 was lost." (PMID 38427106, 2024). "By which mechanisms does HLA-G specifically regulate immune cells or tumor cells to exert immunosuppressive functions?" (PMID 38310272, 2024). "Ectopic expression of HLA-G in tumor and in virally infected cells has also been reported, where it binds leukocyte immunoglobulin-like receptors (LILR) subfamily B and likely operates as a checkpoint inhibitor, dampening NK cell activity." (PMID 39050850, 2024). "The anti-HLA-G monoclonal antibody 87G, for example, counters immune suppression and enhances anti-tumor immunity in vitro and in vivo." (PMID 38342925, 2024). "Another clinical trial is currently evaluating the safety, tolerability, pharmacokinetics, immune response, and preliminary anti-tumor activity of the RO7515629 drug in participants with advanced or metastatic solid HLA-G+ tumors (NCT05769959)." (PMID 38067396, 2023). "HLA-G can also hinder the movement of immune cells towards the cancer site, which decreases the effectiveness of the immune response against the tumor." (PMID 37048814, 2023). "The expression of HLA-G promotes tumor immune escape by modulating both the phenotype and function of immune cells leading to immune evasion and metastasis." (PMID 37630236, 2023). "Consistent with this, we confirmed that un‐engineered Vδ2 γδT cells are still potent cytotoxic to HLA‐G and/or PD‐L1‐silenced tumor cells." (PMID 37078788, 2023). "HLA-G molecules are ligands for the inhibitory immune receptors, LILRB1 and LILRB2 (also known as ILT2 and ILT4), and are frequently expressed by solid tumors, therefore, anti-HLA-G CAR-NK can both target tumor cells and relieve immunosuppression." (PMID 37388731, 2023). "The in vivo experiments provided further evidence that engineering with HLA‐G‐targeted Nb‐CAR redirected γδT cells to tumor lesions and the secreted PD‐L1 Nb‐BiTE recruited T cells to infiltrate and accumulate in the local tumor foci." (PMID 37078788, 2023). "Using in vitro and in vivo models, they found that HLA-G-targeting CAR-NK cells were capable of reducing xenograft tumor growth while extending the median survival in orthotopic mouse models of triple negative breast cancer and glioblastoma." (PMID 38067396, 2023). "HLA-G is a novel immune checkpoint molecule that is ectopically expressed in tumour cells and has an antitumour immune function." (PMID 36053326, 2023). "It has been reported that HLA-G can be found in the tumor cell membrane, free in plasma, or as a membrane bond molecule on tumor cells-derived exosomes." (PMID 37573450, 2023). "The contrasting profile between the high HLA-G expression in the tumor microenvironment and the low plasma sHLA-G levels in PTC patients is still poorly understood." (PMID 37629044, 2023). "It is well known that HLA-G is ectopically expressed in various kinds of cancers, participating in tumor progression and patient survival." (PMID 37875821, 2023). "HLA-G has potent co-inhibitory effects on an anti-tumor immune response compared to other immune checkpoint molecules." (PMID 37630236, 2023). "In Ewing sarcoma, MHC class I molecule HLA-G is expressed on both tumor cells and tumor-infiltrating lymphocytes." (PMID 37424864, 2023).